CDK4 (cyclin dependent kinase 4)
Diseases named in the same sentence as CDK4 in open-access papers (continued):
Sharing a sentence is not in itself a finding about the gene and the disease.
tumor (continued). "As other studies reported factors such as pain reduction and advantageous tumor response for patients receiving a CDK4/6 inhibitor in addition to endocrine therapy, our findings offer a plausible reflection of CDK4/6 inhibitors’ HRQoL profile." (PMID 34636732, 2021). "Intriguingly, they found that a combination of CDK4/6 inhibitor with anti-PD-1 immunotherapy enhances tumor regression and markedly improves overall survival rates in mouse tumor models." (PMID 33668805, 2021). "Susceptibility to CDK4/6 inhibition was confirmed both in vitro in ATRT cell lines and in vivo in an ATRT tumor-bearing mouse." (PMID 34439268, 2021). "The combination of CDK4/6 inhibition and chemotherapy has also been shown to be beneficial, although with varying efficiency depending on the tumor entity." (PMID 33923231, 2021). "In contrast, only small areas, if any, of degeneration and reactive fibrosis were observed in tumors treated with combined CDK4/6i and fulvestrant, and the vital tumor tissue area was much larger in these tumors." (PMID 34433817, 2021). "Cyclin-dependent kinase 4 (CDK4) when hyperactivated drives development and maintenance of most tumour types, thus prompting its use as an essential cancer treatment target and a diagnostic tool." (PMID 34930213, 2021). "The combination of daily oral administration of CDK4/6 inhibitors (Abemaciclib or Palbociclib) and intraperitoneal anti-PD-1 treatment markedly suppressed tumor growth, compared with anti-PD-1 or CDK4/6 inhibitor alone." (PMID 34975505, 2021). "A human anti-cyclin D1 scFv with high antigen affinity and specificity which was recently obtained via screening of phage display antibody libraries, was shown to induce an excellent anti-tumour effect by inhibiting activation of CDK4 present within cells." (PMID 34930213, 2021). "Our findings demonstrate that the combined inhibition of FGFR/CDK4/6 pathways is highly effective in providing long‐lasting tumour growth inhibition and cell differentiation and reducing drug resistance." (PMID 33179425, 2021). "We found that among all the elements (including age, gender, tumor stages T, M, and N classifications of CRC, and gene expressions of CDKs), age and CDK4 expression were the two independent risk factors for the occurrence of CRC." (PMID 34595111, 2021). "In the 393P tumor model, combination of CDK4 and MEK inhibitor scored as synergistic using the Bliss effect analysis." (PMID 34309585, 2021). "The majority of the tumor cells were positive for CDK4 staining and cyclin D1 staining in the nuclei." (PMID 34395284, 2021). "As CDK6 plays an important role in T cell development and CDK4/6 inhibitors boost T cell-mediated anti-tumor immunity, we here aimed to delineate T cell-intrinsic functions of CDK6 focusing on peripheral CD8+ T cells." (PMID 34248938, 2021). "In tumor cells, the over-activated CDK4/6 destabilizes the genome and chromosome, leading to uncontrolled proliferation and ultimately abnormal cell cycle regulation." (PMID 33980246, 2021). "PD‐0332991 is a potent CDK4/6 inhibitor that inhibits the cell cycle arrest of tumor cells in the G1 phase." (PMID 33534964, 2021). "Together, these findings support the addition of AKTi to the standard combination of fulvestrant and CDK4/6i to maintain inhibition of tumor growth in fulvestrant-resistant tumors." (PMID 34433817, 2021). "Growing evidence has proven that CDK4/6 plays a key role in tumor immunity and the prognosis of many cancers." (PMID 35095879, 2021). "With RNA-seq and tumor xenograft models, we evaluate the therapeutic efficacy of combination of CK1i and CDK4/6i in arresting cell cycle progression and retarding tumor growth." (PMID 34508104, 2021). "Purified AK2 bound to rhCDK4 with high specificity and affinity and recognised and interacted specifically with endogenous CDK4 within tumour cells." (PMID 34930213, 2021).
tumor (continued). "Palbociclib, ribociclib, and abemaciclib are administered orally, and dosed chronically to inhibit CDK4/6-dependent tumor cell proliferation." (PMID 34307165, 2021). "The CDK4/6 inhibitor, rafoxanide, decreases total and phosphorylated CDK4/6, cyclin D1, and pRB thus suppressing the G1/S transition and reducing cSCC tumor volume in mice." (PMID 34553848, 2021). "Ribociclib is a selective strong inhibitor of CDK4 and CDK6, blocks Rb phosphorylation, and causes cell cycle arrest of Rb-positive tumor cells, similarly to palbociclib." (PMID 34445095, 2021). "In summary, this study evidenced that licorice induced G0/G1 phase cell cycle arrest by down-regulating CDK4-Cyclin D1 complex on tumor cells." (PMID 34641869, 2021). "The crosstalk between the PI3K-mTOR and CDK4/CDK6 paths provides a strong rationale in combining both routes to inhibit tumor growth." (PMID 34361615, 2021). "Using xenograft and PDX models, we further demonstrate that combined inhibition of CK1ε and CDK4/6 results in marked suppression of tumor growth in vivo." (PMID 34508104, 2021). "With dose escalation of single-agent treatment, reciprocal pathway activation occurred, while combination treatment with both drugs suppressed MAPK and CDK4 pathways and enhanced tumor cell killing." (PMID 34309585, 2021). "Inhibition of CDK4/6, or likewise knocking out Cyclin D1 or overexpressing p16INK4A, leads to increased PD-L1 expression in numerous cell lines and preclinical tumor models, including B16 melanoma." (PMID 34025662, 2021). "Overall, it appears that CDK4/6 inhibition leads to less or equal absolute numbers of CD3+ T cells in the tumor microenvironment, suggesting a possible anti-proliferative effect of CDK4/6i on these cells." (PMID 34025662, 2021). "CDK4/6i as monotherapy reduced tumor growth over a period of 6 weeks, but both double and triple combinations inhibited growth to a greater extent (p = 0.02 and p = 0.01, respectively) and resulted in tumor regression." (PMID 34433817, 2021). "The resulting anti-tumor efficacy of this combination schedule was attributed to CDK4/6 inhibition promoting and maintaining a T cell inflamed microenvironment." (PMID 34025662, 2021). "Combination of CDK4 and MEK inhibitor induced a senescence-associated secretory phenotype that provoked a natural killer cell surveillance program and resulted in tumor cell death." (PMID 34309585, 2021). "In the Cox model, PR-negative tumour (HR, 2.37; 95% CI, 1.45–3.88; p = 0.001) and CDK4/6i dose reduction (HR, 1.51; 95% CI, 1.06–2.16; p = 0.022) predicted worse PFS." (PMID 34207443, 2021). "After determining that this was indeed a mechanism cells used to bypass CDK4/6 inhibition, they performed more relevant preclinical studies to determine the effect this drug had on tumor growth in vivo." (PMID 34830174, 2021). "Compared with CDK4/6 inhibitors, these degraders can show stronger protein degradation ability at 100 nM and better anti-tumor cell proliferation activity than inhibitors." (PMID 34249939, 2021). "In COAD, CDK-1 and CDK-4 clearly shows significant positive correlations with tumor purity while in READ, only CDK-4 was positively correlated with tumor purity." (PMID 33732631, 2021). "This changed rapidly in 2017 when a seminal study uncovered a role for CDK4/6i in augmenting anti-tumor immunity, prompting a spate of further studies in this area." (PMID 34025662, 2021). "Small molecule CINK4 is a triaminopyrimidine derivative specially designed to inhibit the activity of CDK4 in tumor cells." (PMID 35002699, 2021). "Further combining EGFRi with CDK4/6 inhibitor had additive effect on decreasing tumor growth in animal model." (PMID 34204797, 2021). "The RB1 tumour suppressor is activated downstream of CDK4 and CDK618 and its deletion predicts a mechanism for resistance to CDK4/6 inhibitors." (PMID 34580349, 2021).
tumor (continued). "The use of immune competent mouse tumor models is critical to observe that response and accurately evaluate the efficacy of dual therapies targeting CDK4/6 and MEK, such as palbociclib plus mirdametinib." (PMID 33456709, 2021). "To date, trilaciclib has primarily been studied in patients with ES-SCLC, a CDK4/6-independent tumor." (PMID 34307165, 2021). "Since p16 is a critical regulator of CDK4/6-RB signaling preventing G1/S cell cycle progression, p16 deletion/functional loss likely cooperates with the CRTC1-MAML2 fusion in tumor progression." (PMID 33830080, 2021). "When thinking about preventing cell cycle progression and proliferation of tumor cells, CDK4/6 inhibitors are very efficient." (PMID 35002699, 2021). "For the treatment of other groups, it is well established that the effects of CDK4/6 inhibitors reduce the activity of the E2F target DNA methyltransferase 1 and suppress the proliferation of tumour cells and regulatory T cells." (PMID 34059019, 2021). "Ribociclib is a cyclin-dependent kinase inhibitor and helps slow the growth of cancer cells by inhibiting CDK4/6 by arresting cells at the G1 checkpoint, preventing tumor cells from proliferating." (PMID 36303724, 2021). "p16ink4a exerts tumor suppressive function by inhibiting the activities of the cyclin D-dependent kinases, CDK4 and CDK6, and preventing the retinoblastoma protein (Rb) phosphorylation and dissociation from the transcription factor E2F1." (PMID 34277422, 2021). "The expression of FRS2 was also compared with that of classic immunomarkers (MDM2 and CDK4) of this tumor entity." (PMID 34696768, 2021). "Blocking this cyclin D1–CDK4/6-pRb signaling pathway enables CDK4/6i to arrest the proliferation of tumor cells." (PMID 32784518, 2020). "With respect to therapeutic vulnerabilities, activation of the CyclinD – CDK4/6 pathway can sensitize tumor cells to CDK4/6 inhibitors in HNSCC." (PMID 33142242, 2020). "For example, an experimental cytotoxic drug delivery system based on the upregulation of SA‐β‐gal cleared senescent tumor cells induced by the CDK4/6 inhibitor, palbociclib, and resulted in dramatic tumor xenograft regression." (PMID 32652830, 2020). "A combination of OSI-906 and Palbociclib (a CDK4/6 inhibitor) markedly decreased tumor growth in a PDOX model by suppressing the CDK4/6 and IGF-1R pathways." (PMID 32754598, 2020). "Further, we can explain the anti-tumor response of anti-PD-L1 with the use of CDK4/6 inhibitors owing to decreased expression of PD-L1 in G1 phase (that synergizes with anti-PD-L1 therapy)." (PMID 32961872, 2020). "Preclinical studies have supported the marked anti-tumor activity of the CDK4/6 inhibitor palbociclib in ER-positive breast cancer cells." (PMID 32210163, 2020). "Though pRb is primarily a tumor suppressor, deregulation of pRb pathway components, such as loss of the CDK inhibitor p16, amplification of Cyclin D1, or mutation of CDK4 is observed in a variety of tumors." (PMID 33396222, 2020). "For example, a CDK4/6 inhibitor and anti‐PD‐1 immunotherapy enhanced tumor regression and overall survival rates of tumor‐borne mice, and blockade of PD‐L1 potentiated poly‐ADP‐ribose polymerase (PARP) inhibitor anticancer therapies." (PMID 32941674, 2020). "Histopathological findings revealed adipose tissue with lipoblasts and spindle cells and immunohistochemical staining (IHC) revealed the tumor cells were strongly positive for CDK4 and MDM2." (PMID 32438529, 2020). "It is well known that, the three ubiquitinated substrates of FBX8, HIF-1α, CDK4 and C-Myc, are closely related to tumor progression." (PMID 32796813, 2020). "In this context, it is worth mentioning a recent study showing that the specific CDK4/CDK6 inhibitor Abemaciclib promoted anti-tumor immunity through ICD induction." (PMID 32455811, 2020).
tumor (continued). "A strategy targeting both MEK and CDK4/6 not only delays tumour progression but also increases T-cell infiltration and tumour sensitivity to immune checkpoint inhibitors in xenograft models." (PMID 33008426, 2020). "The in vivo anti-tumour activity of volasertib was assessed in comparison with the CDK4/6 inhibitor palbociclib and the FGFR1/2/3 inhibitor AZD45479, as monotherapies or in combination with fulvestrant." (PMID 32792481, 2020). "Sustained tumor regressions were observed for over 9 weeks post-drug withdrawal in xenografts treated with CDK4/6:PI3K:ER combination therapy." (PMID 32795346, 2020). "Further, ST3Gal IV overexpression increased the Jagged1, Notch1, Hes1, Hey1 and p21 expression, meanwhile, decreased the expression levels of CyclinD1, CyclinE1, CDK2 and CDK4 in xenograft tumor tissues." (PMID 33598419, 2020). "In this pre-clinical study, we demonstrate that the simultaneous combination of the CDK4/6 inhibitor palbociclib with regorafenib induces enhanced anti-tumor effects in HCC cell models." (PMID 33072590, 2020). "These tumor suppressors inhibit CDK4 kinase and have the regulatory role in controlling the cell cycle and progression and their deletions are important in children with ALL." (PMID 33369444, 2020). "Across a large cell panel, the activity profiles of abemaciclib and palbociclib were closely related (p < 0.001), and RB1 depletion conferred resistance to abemaciclib, suggesting that the predominant anti-tumor activity is driven by CDK4/6 inhibition." (PMID 32391118, 2020). "We also measured AKT, p-AKT Ser 473, GSK 3β, p-GSK 3β Ser 9, CDK4, and cyclin D1 in tumor tissue by western blotting." (PMID 31832810, 2020). "In summary, we first demonstrated that the combination of metformin with a CDK4/6 inhibitor can provide a remarkable therapeutic advantage against three tumor types over either agent alone." (PMID 32811807, 2020). "Specifically, tumor-associated microglia (TAM) in tumors from Cyclin D1 and CDK4 knockout mice show a cell morphology characterized by multiple protrusions associated with a reduced state of activation." (PMID 33317149, 2020). "Conversely, loss of the endogenous CDK4/6 inhibitors (CDKN2A, CDKN2B, CDKN2C, and CDKN2D) or RB-family (RB1, RBL2, and RBL1) are also observed in specific tumor settings, in total the RB-pathway is subject to genetic perturbation in greater than 30% of tumors." (PMID 32242058, 2020). "It has been reported that aberrant NF-κB activation depends on CDK4/6-mediation and contributes to tumor cell progression." (PMID 33041664, 2020). "Typical GBM alterations, such as IDH mutation, NF1 inactivation, and CDK4-MARCH9 locus amplification, characterize tumor-associated immunosuppression." (PMID 33228738, 2020). "To validate the results from RNAseq, we measured expression of six genes (COL1A1, FN1, MMP2, TFPI2, CDK6, and CDK4) that were significantly up-regulated in tumor cells compared to normal epithelium by RT-qPCR." (PMID 33142242, 2020). "Cyclin D1 and CDK4/6 play a crucial role in G1/S cell cycle progression by phosphorylating and inactivating the Rb, a tumor suppressor that restrains G1/S cell cycle transition." (PMID 33139730, 2020). "We were able to demonstrate a reduction in CDK4/6-regulated gene expression in six patients with evaluable paired tumor biopsy samples." (PMID 32642630, 2020). "In vivo preclinical studies have further verified the radiosensitization effects of CDK4/6 inhibitors, including prolonging the median survival time, reducing tumor volume, and delaying tumor regeneration." (PMID 32933570, 2020). "Simultaneous inhibition of CDK4/6, the main binding partner of cyclin D thus represents a promising treatment strategy to block proliferation of tumor cells and delay or overcome resistance to MAPK inhibitors." (PMID 33255177, 2020).
tumor (continued). "CDK4/6 inhibitors increase the expression of PD-L1 (programmed cell death ligand 1), thus inducing the inflammatory microenvironment and improving tumor immunogenicity." (PMID 33364954, 2020). "Recently, a RB-derived S249/T252 phosphorylation-mimetic peptide, which can overcome undesired tumor immune evasion induced by radiotherapy or CDK4/6 inhibitors, was described." (PMID 32486375, 2020). "We created an in vitro 3D spheroid coculture system modeling tumor heterogeneity dynamics with respect to sensitive and resistant cells towards the primary CDK4/6-inhibitor treatment." (PMID 32565737, 2020). "NFAT1 has been shown to function both as a tumor suppressor through the transcriptional activation of the CDK4 promoter or as an oncogene by silencing p15 expression." (PMID 32363002, 2020). "The p16 was widely known as a tumor suppressor inhibiting the CDK4 and CDK6, impeding the process from G1 to S phase." (PMID 32628820, 2020). "It was previously shown that insulin-like growth factor 1 receptor (IGF-1R) inhibition enhanced the effect of CDK4/6 inhibitors on suppression of ES cell proliferation and tumor formation." (PMID 32477459, 2020). "In recent years, CDK4/6 inhibitors have also been shown to enhance tumor immunogenicity by increasing surface MHC class I expression and boosting T cell activation and infiltration." (PMID 32488085, 2020). "CCT020312 suppressed tumor growth and reduced the protein levels of CDK4 and CDK6 in MDA-MB-453 xenograft mice." (PMID 32508655, 2020). "The gene deletion of CDKN2A and CDKN2B in tumor cells resulted in high activities of CDK4/CDK6, and made cells transit from G1 phase to S phase leading to rapid cell proliferation." (PMID 32860670, 2020). "In conclusion, the genetic make-up of the primary tumour appears insufficient to determine sensitivity or resistance to CDK4/6 inhibition." (PMID 32307447, 2020). "Since the first approval in 2015, the expanded use of CDK4/6i in additional tumor types has been an area of great interest due to the potency of this drug, as well as its unique mode of action." (PMID 32843618, 2020). "Combination treatment with an IGF-1R inhibitor and CDK4/6 inhibitor demonstrated synergistic activity by inhibiting tumor growth and survival of ES cells in vivo and in vitro through the suppression of PKC/AKT/mTOR and activation of RB." (PMID 32754598, 2020). "In non–small‐cell lung cancer, miR‐134 inhibited the expression of cyclin D1/2 and cyclin‐dependent kinase 4 by up‐regulating the expression of P21, thereby inhibiting the proliferation of tumour cells." (PMID 32916774, 2020). "CDK4 was upregulated in 73% of the HCC samples and expression of CDK4 correlated with tumor size and stage." (PMID 32018226, 2020). "Radiotherapy or CDK4/6 inhibitors abolish Rb phosphorylation, with the aim to induce cell cycle arrest in tumor cells, which undesirably also contributes to tumor immune evasion by enhancing PD-L1 expression." (PMID 32486375, 2020). "Palbociclib, a small molecule inhibitor of CDK4/6, has shown anti-tumor activity in vitro and in vivo, with recent studies demonstrating a functional role for palbociclib in reprogramming cellular metabolism." (PMID 32624705, 2020). "Pre-treatment with PD synchronized the tumour cell cycle through the CDK4/6-cyclin D1-RB-E2F pathway, which increased the antitumour effect of CDDP." (PMID 33061853, 2020). "Cell cycle activity was recently reported to correlate with increased anti-tumor immunity in multiple cancers, and CDK4/6 inhibition was reported to trigger anti-cancerous immunity." (PMID 32650578, 2020). "This study was designed to investigate the anti-tumor activity of the CDK4/6 inhibitor, abemaciclib, as a single agent and identify an optimal combination agent with abemaciclib in CRC cell lines." (PMID 32899250, 2020).